JAG1 (jagged canonical Notch ligand 1)
Diseases named in the same sentence as JAG1 in open-access papers (continued):
Sharing a sentence is not in itself a finding about the gene and the disease.
tumor (continued). "We confirmed that the differences in tumor cell proliferation was not the result of E4-EC accelerated death due to Jag1 silencing by examining DNA synthesis in E4-ECs by EdU incorporation assay and found that DNA synthesis (S phase) decreased in E4-ECsJag1KD co-cultured with MDA-231 cells." (PMID 25380486, 2014). "Indeed, several of the identified genes in our study are reported to be involved in angiogenesis, tumor angiogenesis and arteriogenesis, i.e. IL-8, ET-1, CARP, HPTPη, ID1, MGSA, SMAD7, HO-1, RHOB, PTHLH, SERPINH1/HSP47, JAG1, GNA13 and TEAD4." (PMID 16594992, 2006). "However, our data suggest that inhibition of JAG1 even transiently is sufficient to significantly affect ATL tumor cell migration, which may be a function of JAG1 independent of Notch signaling and warrants additional studies." (PMID 30231940, 2018). "JAG1 is upregulated in GBM than in non-tumor cells, and its expression correlates with tumor aggressiveness." (PMID 38092725, 2023). "To dissect the interactions of the tumor microenvironment, we explored the intercellular communication between the JAG-positive and JAG1-negative groups." (PMID 36923423, 2023). "We showed that Jagged1 is a novel proteolytic target of Kras signaling, which induces Jagged1 processing/activation resulting in Jag1-ICD release, which favors tumor development in vivo, through a non-canonical mechanism." (PMID 35847908, 2022). "Unlike DLL4, JAG1 expression in ECs has been shown to have proangiogenic functions; to antagonize DLL4/Notch signaling but also to promote vascular maturation and so to aid tumor growth." (PMID 28533486, 2017).
cancer (238 papers, 2009 to 2026). A tumor composed of atypical neoplastic, often pleomorphic cells that invade other tissues. "Its dysregulation, particularly due to the overexpression of JAG1, is detected in diverse cancers and implicated in various hallmarks of cancer." (PMID 36979394, 2023). "The introduction of high-levels of JAG1 can dramatically increase the risk of hyperplasia and cancer since cell-cell based contact inhibition and proliferation is greatly influenced by Notch signaling." (PMID 34497511, 2021). "JAG1 is part of the Notch signaling pathway and has been associated with disease progression and poor outcome in various cancer entities." (PMID 32756406, 2020). "JAG1 in turn acts as a ligand to the canonical Notch signaling pathway, in which over-expression of JAG1 and/or aberrant activation of the Notch pathway is associated with cancer." (PMID 36046775, 2020). "Inflammatory cytokines or dysregulated NIK expression induced this activation and caused the upregulation of JAG1 expression in normal cancer cells." (PMID 32984007, 2020). "Several studies have functionally linked JAG1 to “stemness” in cancer, and it appears to be the main ligand driving CSC Notch signaling." (PMID 25309874, 2014). "Aberrant upregulation of JAG1 has been reported to be associated with human cancer development and progression." (PMID 24659709, 2014). "However, the level of JAG1 expression must be well-controlled, and constitutive expression must be avoided, as it is known that JAG1 overexpression has been linked to many cancer types." (PMID 34497511, 2021). "We also observed somatic variants in several known cancer-associated genes (for example, JAG1, PRDM2, PRDM8, SETD2, ASPM, ZIC, GRIK1, etc.), which may be important for cell growth and proliferation." (PMID 30871634, 2019). "The first discovery of JAG1 associated with cancer was reported in 2005." (PMID 29464926, 2018). "This indicates that E6 and E7 oncogenic proteins of HPV can interact with the activated JAG1 which in-turn activate various pathways associated in cancers and altogether synergizes with each other, inhibiting apoptosis, promoting cell proliferation and tumorigenesis." (PMID 29921897, 2018). "JAG1 encodes a ligand for receptor Notch 1, functioning in the Notch signaling pathway which is important for multiple cellular functions, especially during normal development and pathogenesis of cancer." (PMID 28828242, 2017). "High JAG1 expression is closely associated with cancer progression and poor patient survival." (PMID 28203521, 2016). "In addition, high JAG1 expression is associated with PC recurrence after radical prostatectomy for clinically localized disease, while CSCs have been suggested to be responsible for cancer recurrence." (PMID 36428807, 2022). "Dll4 was expressed in cancer cells and engaged Notch1 signalling in an autocrine way, whereas Jag1 was expressed in neighbouring hepatic stellate cells and engaged Notch2 signalling in neighbouring cancer cells." (PMID 40052152, 2025). "By deleting Jag1 in each model, we have identified subtype-specific cancer-suppressing and promoting functions for Jagged1." (PMID 39890784, 2025). "The Jag1-ICD/SMAD3–TWIST1 axis represents a novel regulatory pathway that promotes invasive phenotypes in cancer cells, driving brain tumor invasion through a mechanism distinct from canonical TGF-β signaling." (PMID 41294868, 2025). "In cancer, overexpression of the Notch ligand Jag1 in cancer cells activates Notch signaling in TECs, enhancing angiogenesis through proliferation and vessel stabilization." (PMID 38453816, 2024). "Among Notch ligands, JAG1 was most expressed in many clusters, and the expression of receptors showed different patterns across cancer types." (PMID 39074091, 2024).
cancer (continued). "Although cancer invasion and metastasis promoted by EMT are the typical features of malignant tumors, our analysis revealed that in the patients with enriched TGFβ signaling, lower enrichment of JAG1- or NOTCH1-DEGs led to worse prognosis." (PMID 39074091, 2024). "Given findings such as these have made JAG1 inhibitory therapies an attractive target for cancer therapy in these tumors." (PMID 37781534, 2023). "It has been reported that JAG1 overexpression is present in many types of cancer and correlates with a poor clinical prognosis." (PMID 37781534, 2023). "In light of this, these new anti-scFvs and generated anti-JAG1 CARs were made available in the Addgene repository for further exploitation and development and will hopefully enrich the toolbox of cancer therapies targeting JAG1." (PMID 36979394, 2023). "Increased expression of JAG1 is found in various types of cancer (e.g., brain, breast, colorectal, endometrial, gastric, hepatocellular, and prostate) and correlates with poor prognosis." (PMID 36979394, 2023). "In order to inhibit the severe toxicity of pan-Notch inhibitors, JAG1 is receiving increasing attention as a cancer therapeutic target." (PMID 37988196, 2023). "JAG1-targeting therapeutics are expected to provide clinical benefit by impairing therapy-enriched cancer stem cells and reducing metastasis and relapse." (PMID 36979394, 2023). "The role of the NOTCH signaling pathway and JAG1 in different types of cancer development is well established given their involvement in cell proliferation, differentiation, apoptosis, and angiogenesis." (PMID 37781534, 2023). "The development of immunotherapies based on cells expressing chimeric antigen receptors (CARs) against JAG1 would increase the therapeutic potential of targeting JAG1 in cancer treatment." (PMID 36979394, 2023). "A recent study investigated the mechanism that mediates the crosstalk between NOTCH and STAT3 pathways in platinum-resistant ovarian cancer and found that STAT3 and JAG1 are overexpressed in such cancer tissues." (PMID 37781534, 2023). "Jag1 plays a key role in promoting epithelial to mesenchymal transition (EMT) as well as fostering cancer stem cell (CSC) phenotypes." (PMID 36925919, 2023). "JAG1 regulates cell proliferation, survival, and chemotherapeutic resistance in various types of cancers." (PMID 38092725, 2023). "In colorectal cancer, downregulation of miR-34 which targets NOTCH1 and JAG1 involved in cancer stem cell acquisition resulted in increased IL-6 signaling, which led to EMT and cancer metastasis." (PMID 37460910, 2023). "Upregulation of Jagged1 and 2 in MDSCs was largely mediated by cross-talk with cancer cells inducing NFkB-p65-mediated direct binding of Jag1 and 2 promoters and their increased expression." (PMID 38269089, 2023). "Despite its role in disease and cancer, JAG1 has the potential to be a therapeutic molecule for many diseases due to JAG1’s role in cellular proliferation and differentiation." (PMID 37781534, 2023). "The multifunctional role of JAG1 in cancer biology supports the development of anti-JAG1 therapies for the treatment of aggressive tumors." (PMID 36979394, 2023). "JAG1, a ligand of the Notch signaling pathway, regulates cell differentiation and proliferation in various cancers." (PMID 36923423, 2023). "In this study, we established organoid-derived PDAC assembloids that contained endothelial cells and autologous immune cells, and identified JAG1 as a dynamic switch for cancer plasticity in PDAC assembloids." (PMID 35673567, 2022). "This research detected JAG1 expression in 200 BC tissues and 47 para-cancer breast tissues and proved that JAG1 protein was highly expressed in BC tissues compared to adjacent non-cancerous tissue (67.5% vs 23.4%), which was consistent with the literature." (PMID 36539520, 2022).
cancer (continued). "Collectively, these findings support a model in which increased JAG1 expression in ICC/IDC cancer cells induced angiogenesis through NOTCH signaling in vascular endothelial and SMC cells." (PMID 36229464, 2022). "JAG1 overexpression was tied to better OS in stage I, intestinal, poorly differentiated and well differentiated cancer presents." (PMID 36071128, 2022). "Nonetheless, the role played by JAG1 in the stemness and cancer cell plasticity of PDAC remains poorly understood." (PMID 35673567, 2022). "Consistent with elevated JAG1 in ICC/IDC cancer cells, NOTCH target genes were significantly increased in endothelial cells in clusters 0 (HES1) and 22 (HES1 and HEY1) and SMC (HES4) located the ICC/IDC TME compared to benign prostate." (PMID 36229464, 2022). "The high expression rate of JAG1 in BC tissues was 67.5% (135/200), significantly higher than that in para-cancer breast tissues (23.4%, 11/47) (P < 0.001)." (PMID 36539520, 2022). "Dysregulation of Notch signaling has been found in various diseases, including cancer, and several studies reported the involvement of JAG1 in cancer cell invasiveness, EMT, and metastasis." (PMID 35710817, 2022). "Based on the findings that a JAG1-neutralizing antibody blocked the property of cancer cell plasticity, we suggest a humanized JAG1-neutralizing antibody as a potentially new therapeutic for PDAC." (PMID 35673567, 2022). "Dll4 is expressed in cancer cells and activates Notch1 signaling in an autocrine manner, while Jag1 is expressed in the neighboring HSCs and activates Notch2 signaling in adjacent cancer cells." (PMID 35064244, 2022). "WNT5B and TGFB1 expressions were increased in ECs through the interaction with JAG1 on cancer cells." (PMID 35673567, 2022). "In fact, anti-JAG1 antibodies have been proposed as an advanced therapy for cancer patients with high JAG1 tissue expression." (PMID 34067294, 2021). "So far, only JAG1 was found to be upregulated in this type of cancer cells, and also correlated with poor prognosis." (PMID 34944837, 2021). "In other words, we found that NF-κB activation in cancer cells surrounding cancer stem cells induced the expression of JAG1 and activated Notch signaling in cancer stem cells, thereby creating a mechanism to maintain those cancer stem cells (lower half)." (PMID 33840674, 2021). "This last group included genes involved in cell migration and ECM (e.g. RAB6B, FN1, VCAM1 or COL14A1) and genes of signalling pathways usually deregulated in cancer, such as Notch and Wnt signalling (JAG1 and WNT7B, respectively)." (PMID 34353313, 2021). "Ligands are also expressed in most human tissues, including cancer tissues: these are the Jagged 1 and 2 proteins (JAG1 and JAG2), and the delta-like ligands (DLL1, DLL3, and DLL4)." (PMID 34944837, 2021). "For instance, epigenetic heterogeneity and JAG1 signaling were recently shown to jointly promote the persistence of filopodia via the MYO10 in invading cancer cells." (PMID 34831307, 2021). "Only very recently, comparable distinct roles for NOTCH ligands in various cancer types and in connection with certain signaling pathways have been identified, such as for JAG1, DLL1, and DLL4." (PMID 33430387, 2021). "Within the bone niche, cancer cells have been found to express Jag1, which binds its receptor notch, expressed by pre-osteoclasts." (PMID 33143050, 2020). "In particular, ECs express Jag1, which is a ligand for notch that is, in turn, expressed by cancer cells." (PMID 33143050, 2020). "In other tumors, Jag1 promotes cancer stem cell self-renewal, proliferation and stemness maintenance." (PMID 32984007, 2020). "The activation of osteoclasts has been shown to be mediated by cancer cells via the Jag1/notch pathway." (PMID 33143050, 2020). "Studies have demonstrated that JAG1 signaling in cancer cells can activate downstream pathways such as AP-1 (activator protein 1), MAPK (mitogen-activated protein kinases), EGFR (epidermal growth factor receptor), and NF-κB." (PMID 30231940, 2018).
cancer (continued). "Experimental and preliminary clinical targeting of the Notch pathway, particularly of Jag1, has been shown to be promising in multiple cancer types." (PMID 30521558, 2018). "Because JAG1 and Notch-1 are poor prognostic factors in several cancers, it is reasonable to propose that the role of CEA in cancer progression is mediated through JAG1 and Notch-1 expressions in M0 cells." (PMID 29580202, 2018). "Strikingly, NOTCH-induced senescent cells, or cancer cells with high JAG1 expression, drive similar chromatin architectural changes in adjacent cells through cell–cell contact." (PMID 29743479, 2018). "The VEGF/Dll4/Notch pathway also functions in cancer angiogenesis, where changes in the expression levels of signaling molecules, including Notch ligands Dll4 and Jag1, lead to altered morphological features of the vascular endothelium." (PMID 29996493, 2018). "We showed here that Jag-1 expression by cancer cells was important to limit the dependence receptor function of Notch3." (PMID 28719575, 2017). "Our results add Nr2e3 and Ezh2 to the recently identified regulatory interplay between Jag1 and 17beta-estradiol that is important in cancer and other tissue specific disorders including retinal diseases." (PMID 28386079, 2017). "Since JAG1 can increase cancer progression by its pro-proliferative functions, our findings suggest that JAG1's role in cancer progression can be regulated by microenvironmental gal-3." (PMID 28533486, 2017). "Jagged 1 (JAG1) is a ligand that interacts with Notch receptors, and its presence in cancer is correlated with a poor prognosis." (PMID 29230082, 2017). "To verify the effect of BMP9 on NOTCH signaling activation in our cancer model, we used qRT-PCR to quantify the expression of JAG1 after BMP9 stimulation in presence of ALK1Fc or CFc." (PMID 29259971, 2017). "Metastasis, cell proliferation, inhibition of apoptosis, promoting cell survival, and maintaining cancer stem cell populations are all processes regulated by JAG1 via Notch receptor activation." (PMID 29230082, 2017). "JAG1 is an oncogene that promotes metastasis and chemoresistance of a number of cancers through Notch signaling." (PMID 28203521, 2016). "In another set of experiments, we transiently overexpressed either mouse Jag1-Fc or another Notch ligand relevant in cancer, mouse Dll1-Fc in PC3 cells." (PMID 27749937, 2016). "Our results confirmed SOX2 is also a direct transcriptional target of the JAG1/NOTCH signaling pathway in cancer cells." (PMID 27029061, 2016). "Microarray analysis indicated that the enforced JAG1 transcription was associated with an elevated HSPA2 RNA transcription, which played a role in promoting cancer cell migration and invasion." (PMID 26930648, 2016). "Conversely, knockdown of JAG1 with siRNA in highly invasive cancer cells led to the reduction of migration and invasion." (PMID 26930648, 2016). "In this context, JAG1 seems to play a central role in linking various pathways, involving well-established cancer-related molecules such as Notch3, interleukin-6 (IL-6), carbonic anhydrase IX (CAIX), and NF-κB." (PMID 25309874, 2014). "Being a key component of the Notch signaling pathway, JAG1 plays an important role in both physiological and pathological conditions, including embryonic development and cancer." (PMID 25309874, 2014). "This activation significantly augmented the expression of JAG1 in the astrocytes, and the direct interaction of the reactivated astrocytes and cancer stem-like cells (CSCs) significantly stimulated Notch signalling in CSCs." (PMID 23495140, 2013). "Similarly, the NF-κB signaling pathway is significant in various diseases, including cancer; IL-1β can reduce the expression of miR-506 through this pathway, leading to increased Jagged 1 (JAG1) expression and exacerbating the progression of OS." (PMID 40248198, 2025).